NECTIN4 (nectin cell adhesion molecule 4)
Diseases named in the same sentence as NECTIN4 in open-access papers (continued):
Sharing a sentence is not in itself a finding about the gene and the disease.
asthma (3 papers, 2022 to 2025). "Nectin‐4 could serve as a novel diagnostic marker of asthma." (PMID 35386300, 2022). "Plasma nectin-4 levels were higher in patients with asthma than in controls and correlated with lung function." (PMID 41303221, 2025). "The aims of this study were to elucidate the role of Nectin4 in airway inflammation and to determine the relationship between Nectin4 and clinical variables in patients with asthma." (PMID 36457999, 2022). "In our study, Nectin4 protein expression was increased in the blood of asthma patients, and in the lung tissue in a mouse model of asthma." (PMID 36457999, 2022). "In this study, we explored the role of Nectin4 and its participation in Src/Rac1 signaling in asthma." (PMID 36457999, 2022). "Little is known about how Nectin4 regulates target protein levels and apoptosis, especially in asthma." (PMID 36457999, 2022). "Our study examined the involvement of Nectin4 in asthma by assessing airway responsiveness and inflammation in Nectin4−/− mice." (PMID 36457999, 2022). "A Nectin4 cutoff of 72.54 pg/mL distinguished between asthma patients and controls with 70.25% accuracy, 82.4% sensitivity, and 58.1% specificity." (PMID 36457999, 2022). "We detected nectin‐4 in the plasma of patients with asthma using qRT‐PCR, explored the relationship of clinical variables." (PMID 35386300, 2022). "Nectin4 was shown to be highly expressed in the lung tissue of asthmatic mice, with increased levels also measured in the blood of patients with asthma." (PMID 36457999, 2022). "The detection of a circulating form of Nectin4 in the blood of patients with asthma suggests the involvement of Nectin4 in the initiation of airway inflammation via a mechanism that includes the Src/Rac1 cascade pathway." (PMID 36457999, 2022). "In accordance with previous studies, in this study Nectin4/Afadin was expressed in the inflamed airway tissue in a mouse model of asthma." (PMID 36457999, 2022). "We also investigated the relationship between clinical variables and plasma Nectin4 levels in patients with asthma." (PMID 36457999, 2022). "However, the sensitivity and specificity of nectin‐4 require further assessment and comparison with those of recognized asthma tests." (PMID 35386300, 2022). "The ROC curves for Nectin4 levels differed between asthma patients and controls." (PMID 36457999, 2022). "qRT‐PCR revealed that plasma nectin‐4 mRNA levels were higher in asthmatics than controls; this may aid asthma diagnosis and monitoring." (PMID 35386300, 2022). "The relationship of Nectin4 levels to lung function and airway responsiveness suggested the secretion of a circulating form of Nectin4 in patients with asthma, and thus its utility both as a blood marker for the diagnosis of asthma and monitoring of disease progression." (PMID 36457999, 2022). "In conclusion, our study demonstrated the potential role of Nectin4 in asthma." (PMID 36457999, 2022). "Nectin4 may therefore be a biomarker and potential therapeutic target in asthma." (PMID 36457999, 2022). "Nectin-4 knockdown resulted in lower levels of airway inflammation and dysfunction in OVA-induced asthma." (PMID 41303221, 2025). "In our study, Src and Rac1 protein expression were increased in the lung tissue of a mouse model of asthma, and in NHBE cells treated with Der p1, indicating that Src/Rac1 signaling is involved in Nectin4 expression." (PMID 36457999, 2022). "Neither the biological significance nor clinical potential of Nectin4 for asthma has been investigated." (PMID 36457999, 2022). "In this study, we investigated whether the absence of Nectin4 contributes to the pathogenesis of asthma, and the signaling pathways involved in this process." (PMID 36457999, 2022).
cutaneous squamous cell carcinoma (3 papers, 2021 to 2023). "A possible mechanistic explanation for a worse prognosis in patients with low expression of Nectin-4 is a loss of adhesion between cells with an increase of cell migration after Nectin-4 knockdown, as seen in vitro in cutaneous squamous cell carcinoma cells." (PMID 37480387, 2023).
head and neck cancer (3 papers, 2022 to 2023). A primary or metastatic malignant neoplasm affecting the head and neck. "In human, the NECTIN4 expression can be found in the placental and embryonic tissues, as well as in lung, breast, pancreatic, ovarian, and head/neck cancers." (PMID 36140167, 2022). "Thus, Nectin-4 expression in head and neck cancers seems to be similarly high in HNSCC and SGC." (PMID 37480387, 2023).
metastatic colorectal cancer (3 papers, 2022 to 2025). "In a fully immune-competent mouse model of metastatic colorectal cancer, lymphodepletion pretreated mice achieved complete remission with human Nectin4-targeted murine CAR-T (Nectin4 mCAR-T) cells." (PMID 36479116, 2022).
penile squamous cell carcinoma (3 papers, 2023 to 2025). "Further studies examining Nectin-4 and ADCs in penile squamous cell carcinoma should be completed, as high-quality evidence is needed to guide treatment after initial progression for these patients." (PMID 38003302, 2023). "Here, we present a case of metastatic penile squamous cell carcinoma with response to the Nectin-4 inhibitor enfortumab-vedotin-ejfv (EV)." (PMID 38003302, 2023). "Background/Objectives: In a series of 33 patients with advanced penile squamous cell carcinoma (PSCC), we evaluated tissue factor (TF), TROP2, and nectin-4 protein expression as potential therapeutic targets." (PMID 41228204, 2025).
upper tract urothelial carcinoma (3 papers, 2020 to 2024). "Nectin-4 is highly expressed in UC samples, including more than 80% of BCs and more than 60% of upper tract urothelial carcinoma (UTUC)." (PMID 39764422, 2024). "However, the expression status of Nectin-4 in upper tract urothelial carcinoma (UTUC) remains unclear." (PMID 32751328, 2020).
alopecia (2 papers, 2020). Hair loss usually from the scalp. "Toxicities associated with skin (eg, alopecia, dry skin, pruritus, and rash) were expected as Nectin-4 is normally expressed on human skin keratinocytes and appendages." (PMID 31444589, 2020). "Because Nectin-4 has mild to moderate expression on human skin keratinocytes and skin appendages, rash, alopecia, pruritus, and dry skin are likely to be on-target toxicities." (PMID 32031899, 2020).
angiosarcoma (2 papers, 2022). A malignant tumor arising from the endothelial cells of the blood vessels. "Immunocytochemistry revealed stronger NECTIN4 staining intensity in angiosarcoma cells relative to normal endothelial cells." (PMID 35256687, 2022). "Our findings demonstrate the expression and function of NECTIN4 in angiosarcoma and suggest the utility of NECTIN4 as a novel therapeutic target for the treatment of angiosarcoma." (PMID 35256687, 2022). "Nectin4 knockdown also decreased Akt and Src phosphorylation and suppressed angiosarcoma in an in vivo xenograft model." (PMID 36457999, 2022). "NECTIN4 is also expressed in the HAMON and the ISO-HAS-B angiosarcoma cell lines, with NECTIN4 expression higher in angiosarcoma cells than normal endothelial cells." (PMID 35256687, 2022). "Immunohistochemical staining of NECTIN4 was used to investigate NECTIN4 expression in human angiosarcoma lesions." (PMID 35256687, 2022). "NECTIN4 expression was higher in angiosarcoma cells than normal endothelial cells, and angiosarcoma cells were sensitive to monomethyl auristatin E, the cytotoxic part of a NECTIN4-targetting antibody–drug conjugate." (PMID 35256687, 2022). "Because the number of these high-grade samples is still small, continuous assessment of NECTIN4 in these angiosarcoma samples is needed to further evaluate the significance of NECTIN4 in angiosarcoma." (PMID 35256687, 2022). "Next, we investigated the functions of NECTIN4 in angiosarcoma cells by knocking down NECTIN4 using short interference (si) RNA." (PMID 35256687, 2022). "The aims of the present study were to reveal the expression and function of NECTIN4 in angiosarcoma and to assess the utility of NECTIN4 as a target of angiosarcoma treatment." (PMID 35256687, 2022). "NECTIN4 knockdown inhibited the proliferation and angiogenesis of angiosarcoma cells, and Src kinase signaling was shown to be involved in NECTIN4 function, at least in part." (PMID 35256687, 2022). "Because NECTIN4 was expressed in angiosarcoma tissue, we next investigated the functions of NECTIN4 in angiosarcoma using the HAMON and the ISO-HAS-B angiosarcoma cell lines." (PMID 35256687, 2022). "NECTIN4 mRNA and protein was expressed in both normal endothelial cells and angiosarcoma cells, but was significantly higher in angiosarcoma cells." (PMID 35256687, 2022). "Taking the results of this study into consideration, targeting NECTIN4 has further advantages beyond serving as a landmark for drug recognition:NECTIN4 expression was significantly higher in angiosarcoma cells than normal endothelial cells." (PMID 35256687, 2022). "Together, these results imply that NECTIN4 affects the number of viable cells and angiogenesis of angiosarcoma cells partly by controlling Src signaling." (PMID 35256687, 2022). "In this study we focused on NECTIN4 as a potential target of angiosarcoma therapy, and report, for the first time, that NECTIN4 is expressed in angiosarcoma lesions of patients." (PMID 35256687, 2022). "Using immunohistochemistry, we investigated NECTIN4 expression in 74 tissue samples from angiosarcoma patients, finding variable NECTIN4 expression." (PMID 35256687, 2022). "Knockdown of NECTIN4 attenuated cell survival and angiogenesis of human angiosarcoma cells, emphasizing the potential of NECTIN4 as a therapeutic target." (PMID 35256687, 2022). "Based on the results of the present study, we suggest NECTIN4 may be a promising therapeutic target of angiosarcoma because it will support drug recognition of angiosarcoma cells." (PMID 35256687, 2022). "In conclusion, we have revealed that NECTIN4 is expressed in human angiosarcoma tissues." (PMID 35256687, 2022). "To this end, we assessed NECTIN4 expression in angiosarcoma lesions of patients." (PMID 35256687, 2022). "Because NECTIN4 knockdown also decreased Akt and Src phosphorylation, we speculate that these signals are involved in regulation of BCL-2 and/or BAX by NECTIN4 and affects tumor progression of angiosarcoma." (PMID 35256687, 2022).
angiosarcoma (continued). "In addition, NECTIN4 was involved in regulating the proliferation, survival, and angiogenesis of angiosarcoma cells, partly through Src signaling." (PMID 35256687, 2022). "NECTIN4-targeted therapy has the potential to be a novel treatment strategy for angiosarcoma." (PMID 35256687, 2022). "Effects of Src signaling reactivation in NECTIN4-knockdown angiosarcoma cells." (PMID 35256687, 2022). "Thus, NECTIN4-targetting ADC may have a greater effect on angiosarcoma cells than on normal endothelial cells, decreasing adverse effects." (PMID 35256687, 2022). "We also suggest that NECTIN4-targeted therapy may be a promising novel treatment for angiosarcoma." (PMID 35256687, 2022). "In addition, we investigated NECTIN4 expression and function in human angiosarcoma cell lines." (PMID 35256687, 2022). "Thus, it is indicated that NECTIN4 might be involved in the regulation of cell cycle of angiosarcoma cells." (PMID 35256687, 2022). "Thus, NECTIN4 may be involved in the regulation of angiogenesis in angiosarcoma cells through regulating VEGFR2 expression." (PMID 35256687, 2022). "In the present study, NECTIN4 knockdown downregulated BCL-2 and upregulated BAX in angiosarcoma cell lines and induced apoptosis." (PMID 35256687, 2022). "However, the expression and function of NECTIN4 in angiosarcoma remains unknown." (PMID 35256687, 2022). "We also evaluated the effects of the mitosis inhibitor monomethyl auristatin E (MMAE), which is the cytotoxic part of a NECTIN4-targeted ADC, on the viability of normal endothelial cells (HUVEC, HDMEC, and HDBEC) and angiosarcoma cells (HAMON and ISO-HAS-B)." (PMID 35256687, 2022). "However, the significance of NECTIN4 in angiosarcoma remains unknown." (PMID 35256687, 2022). "Both HUVEC and control siRNA-transfected angiosarcoma cells formed tubular structure on ECM gels, but tube formation was obviously inhibited in NECTIN4-siRNA transfected HAMON and ISO-HAS-B." (PMID 35256687, 2022). "Using cell cycle analysis we also found that knockdown of NECTIN4 alter the proportion of G0/G1 and S phase in angiosarcoma cells, i.e. G0/G1 non-proliferating cells were increased in NECTIN4 siRNA-transfected condition." (PMID 35256687, 2022). "Simultaneous treatment with NECTIN4 siRNA and dasatinib did not further decrease the number viable cells in angiosarcoma cell lines." (PMID 35256687, 2022). "It is unknown how NECTIN4 affects VEGFR2 expression, but we found that Src inhibition suppressed VEGFR2 expression in angiosarcoma cells, as seen after NECTIN4 knockdown." (PMID 35256687, 2022). "NECTIN4 was highly expressed in angiosarcoma cells compared with normal endothelial cells." (PMID 35256687, 2022).
bone metastasis (2 papers, 2013 to 2026). Transfer of a neoplasm from its primary site to bones. "This was also the case for Nectin-4 (alive & well 0.382+/−0.207; poor outcome 0.092+−0.087; bone metastasis 0.0053+/−0.005, p = 0.07, significance not reached)." (PMID 24386110, 2013).
diabetes (2 papers, 2022 to 2025). "Focusing on the PPARγ pathway, we identify a mechanism by which UC cells regulate NECTIN4 expression, and we evaluate the effects of PPARγ agonists, which were initially approved for diabetes, on the activity and therapeutic window of NECTIN4-CAR T cells." (PMID 40931013, 2025). "In summary, we found that modulating the PPARγ pathway increases NECTIN4 expression, which we leveraged by repurposing a diabetes drug, rosiglitazone, to increase targeting and anti-tumor efficacy of NECTIN4-CAR T cells." (PMID 40931013, 2025).
head and neck squamous cell carcinoma (2 papers, 2022 to 2025). A squamous cell carcinoma that arises from any of the following anatomic sites: lip and oral cavity, nasal cavity, paranasal sinuses, pharynx, larynx, and salivary glands. "A Phase II clinical trial evaluating EV in head and neck squamous cell carcinoma (HNSCC) is currently underway, underscoring the growing interest in targeting Nectin-4 in this region." (PMID 40699695, 2025).
neuropathy (2 papers, 2020 to 2022). A disorder affecting the nervous system that manifests with pain, tingling, numbness, and/or muscle weakness. "As Nectin-4 is present in normal human skin and neuropathy has been previously reported with microtubule inhibitors like MMAE, treatment-related rash and peripheral neuropathy were expected AEs." (PMID 31444589, 2020).
osteosarcoma (2 papers, 2022 to 2023). A usually aggressive malignant bone-forming mesenchymal neoplasm, predominantly affecting adolescents and young adults. "Nevertheless, the role and molecular mechanism of Nectin-4 in osteosarcoma (OS) are rarely studied." (PMID 35953862, 2022). "Therapeutically, Nectin-4 may serve as a target for the treatment of osteosarcoma." (PMID 35953862, 2022).
pancreatic adenocarcinoma (2 papers, 2015 to 2024). "In contrast, most of the pancreatic adenocarcinoma cases showed negative or focal staining for nectin-2 (median score: 1.0, mean score: 0.76) and nectin-4 (median score: 0, mean score: 0.67)." (PMID 25690753, 2015).
skin cancer (2 papers, 2021). "In normal skin, NECTIN4 is mainly expressed in the epidermal keratinocytes and skin appendages; however, its expression in skin cancers has not been extensively investigated." (PMID 33478111, 2021).
skin reaction (2 papers, 2024 to 2025). "Treatment-related skin reactions (TRSRs) induced by enfortumab vedotin (EV) targeting nectin-4 are among the most common adverse events." (PMID 39681749, 2025).
subacute sclerosing panencephalitis (2 papers, 2021 to 2025). A chronic progressive encephalitis that develops a few years after measles infection and presents with a demyelination of the cerebral cortex. "Very rarely, MV may break into the central nervous system (CNS) and persist independently of SLAM and nectin 4 because neither is expressed in the human CNS, causing a rare fatal neurodegenerative disease, subacute sclerosing panencephalitis (SSPE)." (PMID 34643483, 2021). "MeV may persist in the brain, which does not express SLAMF1 and nectin-4, leading to subacute sclerosing panencephalitis (SSPE) several years after acute infection." (PMID 40192292, 2025).
adenoid cystic carcinoma (1 paper, 2023). A malignant tumor arising from the epithelial cells. "A moderate or high Nectin-4 expression was found in 25.9% of salivary duct carcinomas (SaDu) and in 30.7% of adenoid cystic carcinomas (ACC)." (PMID 37480387, 2023). "As a conclusion, the results of the present study show that Nectin-4 is expressed in primary and metastatic SGC and that a proportion of patients with the prognostically unfavorable entities salivary duct carcinoma and adenoid cystic carcinoma show a moderate or high expression." (PMID 37480387, 2023).
anaplastic thyroid carcinomas (1 paper, 2022). "Trophoblast cell surface antigen 2 and nectin-4 were expressed in 65% and 59% of anaplastic thyroid carcinoma tissues, respectively." (PMID 35158847, 2022). "In contrast, nectin-4 expression was high in patients with de novo anaplastic thyroid carcinoma." (PMID 35158847, 2022). "Therefore, we examined expression rates of the following antibody–drug conjugate targets using the tissue microarrays of anaplastic thyroid carcinomas: human epidermal growth factor receptor 2, nectin-4, trophoblast cell surface antigen 2, glycoprotein non-metastatic B, and B7-H3." (PMID 35158847, 2022).
benign prostatic hyperplasia (1 paper, 2024). A non-cancerous nodular enlargement of the prostate gland. "We determined NECTIN‐4 expression levels through Western blot and flow cytometry in a panel of PCa cell lines (22Rv1, C4‐2B, PC‐3, DU145 and LNCaP) and in a benign prostatic hyperplasia cell line (BPH‐1)." (PMID 39072867, 2024). "Furthermore, our results align with previous research indicating the absence of NECTIN‐4 in PRIM and its expression in benign prostatic hyperplasia." (PMID 39072867, 2024).
brain cancer (1 paper, 2025). A primary or metastatic malignant neoplasm affecting the brain. "Brain cancers had down-regulated NECTIN4 - consistent with their non-epithelial character - and down-regulated IDO." (PMID 40788962, 2025).
Cholecystitis (1 paper, 2023). The presence of inflammatory changes in the gallbladder. "In 63.2% of GBC, nectin-4 was upregulated, but only 1.7% of cholecystitis samples showed positive nectin-4 staining." (PMID 37568798, 2023).
cleft palate (1 paper, 2026). Cleft palate is a fissure type embryopathy that affects the soft and hard palate to varying degrees. "This cooperative role of E- and P-cadherin may parallel that seen between Nectin1 and Nectin4 during palatogenesis, where loss of both adhesion proteins resulted in a severe cleft palate while cleft palate was seen with low penetrance in single knockdowns." (PMID 41231213, 2026).
dry eye (1 paper, 2024). "Enfortumab Vedotin (Padcev) targets Nectin-4 and is linked to blurry vision, dry eye, and the first case of bilateral anterior subcapsular cataract." (PMID 39161379, 2024).
endothelial dysfunction (1 paper, 2022). In vascular diseases, endothelial dysfunction is a systemic pathological state of the endothelium (the inner lining of blood vessels) and can be broadly defined as an imbalance between vasodilating and vasoconstricting substances produced by (or acting on) the endothelium. "In the presented research, we discovered the overexpression of genes, encoding cell adhesion molecules, including the verified marker of endothelial dysfunction SELE, as well as novel NECTIN4." (PMID 36140167, 2022).